HLA-B (major histocompatibility complex, class I, B)
Diseases named in the same sentence as HLA-B in open-access papers (continued):
Sharing a sentence is not in itself a finding about the gene and the disease.
immune disease (6 papers, 2013 to 2025). "In the gene networks associated with the identified immune disease pathways, HLA class I (i.e. HLA-A, HLA-B, HLA-C) are main players in molecular interplays associated with immune disease pathways." (PMID 40580453, 2025). "Therefore, the overexpression of HLA-B, HLA-C and a number of other HLA alleles, as well as the upregulation of certain immune system disease pathways in CCRCC, may be attributed to the self-antigenicity of CCRCC." (PMID 24348776, 2014).
adenocarcinoma (4 papers, 2016 to 2022). A common cancer characterized by the presence of malignant glandular cells. "Thus, controlling for the amino acid positions 13 and 71 in HLA-DRB1, and position 156 in HLA-B, no residual HLA allele or amino acid associations are observed with adenocarcinoma (P > 0.001)." (PMID 28806749, 2017).
bacterial infections (3 papers, 2015 to 2021). "Thus, our in vitro findings seem to provide a hint why HLA-B*57 might be associated with an increased risk to die from bacterial infection in virally suppressed HIV patients." (PMID 33278000, 2021).
cardiovascular disease (3 papers, 2023 to 2026). "Within the HLA-B region, 33 eQTLs were associated with reported GWAS traits including LDL, HDL, TG, total cholesterol levels, as well as cardiovascular disease (CVD), and anthropomorphic measures." (PMID 38384714, 2024).
psychiatric disorder (3 papers, 2020 to 2023). A disorder characterized by behavioral and/or psychological abnormalities, often accompanied by physical symptoms. "Among genes mapped to loci shared between AN and psychiatric disorders, several immune-related genes were implicated, including the C4A, C4B, NCAM1, HLA-B, HLA-C, and HLA-E genes." (PMID 37658054, 2023).
bladder (2 papers, 2023 to 2025). "Additionally, a recent study reported the HLA-B-21M/T was independently associated with bladder patient outcomes and can help to optimize the use of new immunotherapies in these patients." (PMID 41228348, 2025).
genetic disease (2 papers, 2015 to 2022). "In addition, to the best of our knowledge, none of the previous studies of HLA-B AF in Arab countries investigated or reported pharmacogenomic data pertaining to genetic markers for genetic disorders, such as drug hypersensitivity." (PMID 36003520, 2022).
heart disease (2 papers, 2022 to 2023). "HLA-A*11:01-*33:03 (13.7% vs. 7.3%, P value = 0.042) and *02:07-*11:01 (2.7% vs. 12.9%, P value = 0.010), and HLA-B*40:01-*58:01 (12.5% vs. 5.5%, P value = 0.027) were significantly associated with heart disease." (PMID 35321340, 2022). "In this group, genotypes HLA-A*11:01-A*33:03 and A*02:07-A*11:01, as well as HLA-B*40:01-B*58:01 were significantly correlated with heart disease." (PMID 37841270, 2023).
connective tissue diseases (1 paper, 2024). "A complete workup including vasculitides, connective tissue diseases, and human leukocyte antigen (HLA)-B*51 was performed, which revealed a positive HLA-B*51." (PMID 39463588, 2024).
hematologic malignancy (1 paper, 2024). "All patients were to receive either peripheral blood or bone marrow allo-HSCT for hematologic malignancy from unrelated donors who were 8 of 8 or 7 of 8 human leukocyte antigen (HLA)-matched (a single allele mismatch at HLA-A, HLA-B and HLA-C, and HLA-DRB1 was permitted)." (PMID 38844797, 2024).
inflammation (1 paper, 2023). Aberrant reaction of the microcirculation characterized by movement of fluid and leukocytes from the blood into extravascular tissues. "Polygenic BD (HLA-B*51+).Partial response to azathioprine but worsening of ocular inflammation prompted escalation to adalimumab with good effect." (PMID 38006337, 2023).
neurodevelopmental disorder (1 paper, 2020). A behavioral and cognitive disorder with onset during the developmental period that involves impaired or aberrant development of intellectual, motor, or social functions. "Genes implicated in ASD such as Annexin 1 (ANXA1), HLA-B and CNTN6 with deletion or duplication in a spectrum of neurodevelopmental disorders and ID were upregulated in TSC1-Het and Null NPCS when compared with the WT." (PMID 31921404, 2020).
respiratory disease (1 paper, 2023). "This study also reports on the relationship observed between HLA-B*35 with SARS-CoV-2, a second respiratory disease, following a previous study implicating influenza A (H3N2) that suggests that viruses can escape from CD8+ T cells immunity, among other viral pathologies." (PMID 37708194, 2023).
HLA-B also shares sentences with these, for which no sentence is quoted: hyperuricemia (5 papers); thyroiditis (5); ulcerative colitis (5); birdshot chorioretinopathy (4); multiple myeloma (4); Skin rash (4); renal disease (3); bipolar disorder (2); cardiomyopathy (2); cervical squamous cell carcinoma (2); eczema (2); Ewing sarcoma (2); Graves ophthalmopathy (2); head and neck squamous cell carcinoma (2); hyperlipidemia (2); hypothyroidism (2); lung disease (2); lung squamous cell carcinoma (2); meningioma (2); myositis (2); Nephroblastoma (2); Onset (2); Opportunistic infection (2); scleroderma (2); soft tissue sarcoma (2); systemic vasculitis (2); tropical spastic paraparesis (2); viral myocarditis (2); Abdominal obesity (1); acquired aplastic anemia (1).
A further 140 diseases each share a sentence with HLA-B in 1 paper.